CNRIP1 (cannabinoid receptor interacting protein 1)
Description:
[Isoform 1]: Suppresses cannabinoid receptor CNR1-mediated tonic inhibition of voltage-gated calcium channels. [Isoform 2]: Does not suppress cannabinoid receptor CNR1-mediated tonic inhibition of voltage-gated calcium channels.
Synonyms: CRIP-1; C2orf32; DKFZP566K1924; CRIP1; CRIP1a; CRIP1b
Tractability: Antibody: its Gene Ontology location is reachable by antibodies, with high confidence. PROTAC: its protein half-life has been measured.
Gene: Protein-coding gene on chromosome 2 (68,284,171 to 68,320,051, reverse strand). Ensembl gene ENSG00000119865.
Subcellular location (Human Protein Atlas): Cytosol
Gene Ontology:
Molecular function: protein binding; type 1 cannabinoid receptor binding
Biological process: regulation of trans-synaptic signaling by endocannabinoid, modulating synaptic transmission
Cellular component: cytoplasm; plasma membrane; GABA-ergic synapse; glutamatergic synapse; presynapse
Genetic constraint (gnomAD): Loss-of-function variants: 10 observed, 14.4 expected, observed/expected ratio (o/e) 0.69, 90% interval 0.43 to 1.18. The upper end of that interval is the gene's LOEUF score, 1.18, which puts it in group 5 of 6, group 1 being the genes least tolerant of losing a copy. Missense variants: 211 observed, 200.19 expected, observed/expected ratio (o/e) 1.05, 90% interval 0.94 to 1.18. Synonymous variants: 91 observed, 75.31 expected, observed/expected ratio (o/e) 1.21, 90% interval 1.02 to 1.44.
Homologues: Orthologues: chimpanzee CNRIP1 (100% identical), macaque CNRIP1 (100% identical), guinea pig CNRIP1 (98% identical), rabbit CNRIP1 (97% identical), dog CNRIP1 (96% identical), mouse Cnrip1 (96% identical), rat Cnrip1 (96% identical), tropical clawed frog cnrip1 (66% identical), pig CNRIP1 (66% identical), zebrafish cnrip1a (60% identical), zebrafish cnrip1b (60% identical), Caenorhabditis elegans F29A7.4 (28% identical).
Diseases named in the same sentence as CNRIP1 in open-access papers:
CNRIP1 is named in the same sentence as 28 diseases in open-access papers, as found by Europe PMC text mining. Sharing a sentence is not in itself a finding about the gene and the disease. The quoted sentences say what the papers report.
adenoma (5 papers, 2011 to 2025). A neoplasm arising from the epithelium. "Most of the adenomas (n = 12) and carcinomas (n = 55) analyzed were methylated in agreement with the present report, underscoring the potential of CNRIP1 as a novel marker for early detection of colorectal tumors." (PMID 21777459, 2011). "Promoter hypermethylation of the genes CNRIP1, FBN1, INA, MAL, SNCA, and SPG20 was frequent in both colorectal cancers (65-94%) and adenomas (35-91%), whereas normal mucosa samples were rarely (0-5%) methylated." (PMID 21777459, 2011). "Within 60 adenoma samples (median age 67 years) successfully amplified by qMSP, promoter hypermethylation was detected in 90%, 68%, 42%, 85% and 55% for CNRIP1, FBN1, INA, MAL, and SNCA, respectively, and 90% of the adenomas harbored co-methylation." (PMID 21777459, 2011). "Further analysis indicated that the changes in methylation levels of the four iRFE MDGs, ADHFE1-Cluster1, CNRIP1-Cluster1, MAFB, and TNS4, occurred in adenoma tissues, while changes did not occur until stage IV in cell-free DNA." (PMID 36158666, 2022).
colorectal cancer (5 papers, 2011 to 2024). A primary or metastatic malignant neoplasm that affects the colon or rectum. "Some of the downstream effects of CNRIP1 promotor methylation in colorectal cancer have been determined." (PMID 33261012, 2020). "Several studies have focused on the hypermethylation of the CNRIP1 promotor and a small panel of other genes as a biomarker for colorectal cancer." (PMID 33261012, 2020). "Hypermethylation of CNRIP1 exons has also been demonstrated in colorectal cancer using an orthogonal LC-MS/MS-based technique." (PMID 33261012, 2020). "There is evidence that these three genes (FAM123A, CNRIP1 and NALCN) are associated with the risk of colorectal cancer." (PMID 28410574, 2017). "In 2006 we identified CNRIP1 as a promoter methylation target in colorectal cancer by treatment of cell lines with 5-aza 2'deoxycytidine followed by expression microarray analyses." (PMID 21777459, 2011). "The majority of normal mucosa samples from colorectal cancer free individuals (95%) were unmethylated in the CNRIP1 gene promoter." (PMID 21777459, 2011). "Methylation in colorectal cancers ranged from 55% (C3orf14) to 96% (BEX1; median 84%), while methylation in normal tissue was between 0% (CNRIP1, FBN1, INA) and 45% (BEX1; median 5%), P < 0.0001 to P < 0.02." (PMID 21777459, 2011). "CNRIP1, FBN1, INA, MAL, and SNCA promoter methylation was analyzed quantitatively (qMSP) in the colorectal cancer (n = 74; median age 71 years) and normal mucosa (n = 51; median age 55 years) test sets." (PMID 21777459, 2011). "Co-methylation, here defined as simultaneous hypermethylation of two or more of the six gene promoters (CNRIP1, FBN1, INA, MAL, SNCA, and SPG20), was found in 99% of the colorectal cancer test set samples and 2% of the normal mucosa samples." (PMID 21777459, 2011).
schizophrenia (4 papers, 2019 to 2023). A major psychotic disorder characterized by abnormalities in the perception or expression of reality. "Aberrant CNRIP1 DNA promoter methylation was observed in post-mortem in human patients with schizophrenia, and decreased methylation of the CNRIP1 DNA promoter was discovered in the ventral hippocampus of a rodent model of schizophrenia susceptibility." (PMID 36970281, 2023). "Recent work showed that ventral hippocampal overexpression of CNRIP1 would lead to a schizophrenia-like phenotype in the rat." (PMID 36970281, 2023).
intrahepatic cholangiocarcinoma (3 papers, 2022 to 2025). A carcinoma that arises from the intrahepatic bile duct epithelium in any site of the intrahepatic biliary tree. "It was shown that reduced expression of cannabinoid receptor-interacting protein 1 (CNRIP1) was associated with enhanced DNA methylation of a CpG island site named CNRIP1 MS-2 (CNRIP1 methylation site-2) in intrahepatic cholangiocarcinoma (ICC) cells." (PMID 36358910, 2022). "Cannabinoid receptor-interacting protein 1 (CNRIP1) inhibits intrahepatic cholangiocarcinoma cell proliferation, invasion, and migration by modulating the CNRIP1/Parkin/PKM2 pathway, thereby enhancing Parkin-PKM2 interactions and facilitating PKM2 ubiquitination and degradation." (PMID 41169372, 2025). "Overexpression of cannabinoid receptor-interacting protein 1 (CNRIP1) activates Parkin, leading to PKM2 degradation and thereby promoting cell growth and metastasis in intrahepatic cholangiocarcinoma (ICC)." (PMID 35392171, 2022).
colon cancer (2 papers, 2011 to 2024). "Limit studies found that the overexpression of CNRIP1 can reduce the proliferative and migration abilities of colon cancer cells." (PMID 39448550, 2024). "In the evaluated 20 colon cancer cell lines, all but one (UBE3A) gene promoters were hypermethylated with frequencies ranging from 20% (LEF1 and MEF2C) to 100% (CNRIP1)." (PMID 21777459, 2011). "Before drug treatment all colon cancer cell lines tested harbored promoter methylation of CNRIP1, INA, FBN1, and SNCA accompanied by little or no expression of the same genes." (PMID 21777459, 2011).
colorectal adenoma (1 paper, 2011). An adenoma that arises from the colon or rectum. "We have identified four genes, CNRIP1, FBN1, INA, and SNCA that were frequently hypermethylated in colorectal adenomas and cancers." (PMID 21777459, 2011).
colorectal tumor (1 paper, 2011). "By applying DNA methylation microarray analysis and subsequent methylation-sensitive high resolution melting analysis colorectal tumor specific promoter methylation of CNRIP1 was recently confirmed." (PMID 21777459, 2011).
gastric cancer (1 paper, 2020). A primary or metastatic malignant neoplasm involving the stomach. "-Analysis Type: Gastric Cancer vs. Normal Analysis-COL8A1; Analysis Type: Gastric Cancer vs. Normal Analysis-FRMD6; Analysis Type: Gastric Cancer vs. Normal Analysis-TIMP2; Analysis Type: Gastric Cancer vs. Normal Analysis-CNRIP1; Analysis Type: Gastric Cancer vs. Normal Analysis-GPR124." (PMID 32095347, 2020).
glioma (1 paper, 2024). A benign or malignant brain and spinal cord tumor that arises from glial cells (astrocytes, oligodendrocytes, ependymal cells). "Especially, CD300C, CNRIP1 and MYO1F are the top three genes that engage in immune response in the glioma's microenvironment." (PMID 39448550, 2024).
lung adenocarcinoma (1 paper, 2022). A carcinoma that arises from the lung and is characterized by the presence of malignant glandular epithelial cells. "Furthermore, by RNA-Seq, a fusion between PPP3R1 and CNRIP1 genes was observed both in noninvolved tissue and in lung adenocarcinoma tissue." (PMID 36553541, 2022).
rectal cancer (1 paper, 2016). A primary or metastatic malignant neoplasm that affects the rectum. "Ten of the 36 (EYA4, FOXI2, CNRIP1, SFRP1, ADHFE1, C2orf40, MAL, PHACTR3, SST, TMEFF2) were known as rectal cancer related genes with aberrant methylation." (PMID 27566576, 2016).
cancer (5 papers, 2011 to 2022). A tumor composed of atypical neoplastic, often pleomorphic cells that invade other tissues. "The cannabinoid receptors have already joined the many possible targets for cancer treatment, making the recent report correlating CNRIP1 chromosomal modifications on human chromosome 2p13 with cancer an unsurprising one." (PMID 33261012, 2020). "It is important to note that hypermethylation of CNRIP1 has also been observed in other cancer types: cholangiocarcinoma, lung adenocarcinoma, non-Hodgkin lymphoma, and gastric carcinoma." (PMID 33261012, 2020). "The level of mRNA expression of CNRIP1, FBN1, INA, and SNCA was strongly associated with promoter methylation status in cancer cell lines (P = 0.037, P = 0.017, P = 0.006, and P = 0.001, respectively)." (PMID 21777459, 2011). "Hypermethylation of CNRIP1 has been observed in some cancer types." (PMID 36158666, 2022). "Therefore, much work is still needed to understand the role of CNRIP1/CRIP1a in cancer." (PMID 33261012, 2020). "In previous studies, all four genes (ADHFE1, CNRIP1, MAFB, and TNS4) have been reported as cancer-related genes." (PMID 36158666, 2022). "In spite of several genome-wide epigenetic studies, only a few reports include DNA methylation data and potential subsequent epigenetic silencing of CNRIP1, FBN1, INA, and SNCA in cancer." (PMID 21777459, 2011).
tumor (4 papers, 2011 to 2020). "The same treatments also caused a decrease in invasiveness and migration ability, suggesting that CRIP1a is a tumor suppressor and that demethylation of the CNRIP1 promoter could be a potential colorectal therapy." (PMID 33261012, 2020). "Here we found that the DNA methylation of CNRIP1, FBN1, INA, and SNCA was associated with reduced or lost gene expression in cell lines, indicating that they might harbor a tumor suppressor function." (PMID 21777459, 2011).
CNRIP1 also shares sentences with these, for which no sentence is quoted: Alzheimer disease (2 papers); neuroblastoma (2); acne (1); acute myeloid leukemia (1); adenocarcinoma (1); alcohol use disorder (1); asthma (1); Chronic Lymphocytic Leukemia (1); epilepsy (1); Glycogen Storage Disease (1); hearing loss (1); ischemia (1); Liver Carcinoma (1); ovarian carcinoma (1); psychiatric disorder (1).